GAP43 (growth associated protein 43)
Diseases named in the same sentence as GAP43 in open-access papers (continued):
Sharing a sentence is not in itself a finding about the gene and the disease.
ischemia (14 papers, 2009 to 2025). A hypoperfusion of the BLOOD through an organ or tissue caused by a PATHOLOGIC CONSTRICTION or obstruction of its BLOOD VESSELS, or an absence of BLOOD CIRCULATION. "Moreover, our results suggest an association of CSF GAP-43 concentration and clinical characteristics during the first 2 weeks after ischemia." (PMID 30526557, 2018). "Growth-associated protein 43 (GAP-43) is highly upregulated in brain tissue shortly after experimental ischemia suggesting the CSF GAP-43 concentration may be altered in ischemic brain disorders." (PMID 30526557, 2018). "Previous studies of axotomy and experimental models of ischemia, traumatic brain injury, and MS show that GAP-43 protein expression is induced temporarily and adjacent to neuro-axonal damage and the formation of new lesions." (PMID 31754174, 2019). "Upon axotomy and in experimental models of ischemia, traumatic brain injury, and MS, GAP-43 protein expression is temporarily induced adjacent to the lesions." (PMID 31754174, 2019). "In ischemia reperfusion-injured rat model, TSG attenuated animal behavior changes and neurological function scores via increasing the expressions of NGF, growth-associated protein 43, and PKA catalytic subunit proteins." (PMID 29801454, 2018). "Most importantly, expression of GAP-43 is increased in regenerating axons and enhances the sprouting of axons after ischemia." (PMID 28380213, 2017). "Both TTC staining and GAP-43 immunofluorescence labeling results showed that EA treatment reduced ischemia injury and promoted neuroplasticity compared with the model group." (PMID 24348687, 2013). "The expression of GAP43 is greatly increased at the early stage of ischemia." (PMID 37873537, 2023). "Indeed, another report showed that the GAP-43 expression was upregulated in retinal ganglion cells after ischemia-induced damage." (PMID 34567109, 2021). "Furthermore, Que/mAb GAP43-Exo potentially alleviated neuronal injury after ischemia/reperfusion and exerted synergistic therapeutic effects." (PMID 34001136, 2021). "Notably, Que/mAb GAP43-Exo attenuated oxidative stress-induced ischemia/reperfusion injury and induced the activation of the Nrf2/HO-1 pathway by promoting the nuclear translocation of Nrf2 and upregulating expressions of NQO-1, HO-1, SOD1 and GPx1." (PMID 34001136, 2021). "Animal models of ischemia suggest that the content of GAP-43 in the brain may be the result of both an increase due to regeneration responses and a decrease due to disrupted axons at the site of injury." (PMID 30526557, 2018). "Following ischemia, the expression of GAP-43 first increased considerably and then decreased." (PMID 28380213, 2017). "The transient upregulation of GAP43 apparently represents a transition event during the acquisition of a neuronal-like phenotype and a type I diabetic environment attenuated the neurogenic response of cardiac nestin(+) cells to ischemia and 6-hydroxydopamine." (PMID 23938193, 2013). "Concerning GAP-43 expression, 3-AB treatment induces a reduced expression already significant at 8 d and at one month post-ischemia whereas statistical differences were found for synaptophysin expression at longer time points (15 and 30 d of ischemia) between the two groups of animals." (PMID 19956568, 2009). "The aim of this study was to investigate whether exogenous retinoic acid (RA) can upregulate the mRNA and protein expression of growth-associated protein 43 (GAP-43), thereby promoting brain functional recovery in a rat distal middle cerebral artery occlusion (MCAO) model of ischemia." (PMID 28380213, 2017). "Since neuroplastic changes have been shown to be a delayed phenomenon, GAP-43 and synaptophysin expression were investigated by western blotting experiments in the two concentric samples of cortical tissue P1 and P2 at longer time points of ischemia (8, 15 and 30 d)." (PMID 19956568, 2009).
ischemia (continued). "EA and pergolide led to increased GAP-43 expression in DAergic neurons 7 days after the onset of ischemia compared with the model group (P < 0.05) (data not shown) (resp)." (PMID 24348687, 2013).
diabetes (13 papers, 2012 to 2026). "Studies have shown that growth associated protein 43 (GAP43) in immunoreactive nerve fibers is reduced in diabetics." (PMID 41169500, 2025). "Our findings of higher GAP-43 protein levels in diabetic individuals align with research highlighting diabetes as a risk factor for spinal degeneration." (PMID 40004753, 2025). "In streptozotocin-induced diabetes in rats, neuropathy was associated with suppressed mRNA expression of Nfs as well as GAP43 in sensory neurons and their impaired incorporation into distal branches." (PMID 22412941, 2012). "In NOD mice, although diabetes incidence was lower in males than in females, diabetic male mice displayed comparable loss of islet sympathetic innervation and reduced expression of Gap43, Tubb3, and Stmn2." (PMID 41243316, 2026). "Finaly, the results of double-immunostained labeling of KIF5B and GAP-43 protein expression in the rat gastrocnemius muscle showed that compared with the C group, diabetes caused a decreased of KIF5B+ Cells (% GAP-43+) in the gastrocnemius skeletal muscle fibers (p ≤ 0.001)." (PMID 33953268, 2021). "Diabetes significantly predicted GAP-43 protein levels in the study group (coefficient = 0.495; p = 0.029)." (PMID 40004753, 2025). "Perhaps during the early stages of diabetes, an increase in GAP43 expression acts as a protective response to the adverse effects of diabetes on neurons." (PMID 39845838, 2024). "Levetiracetam treatment has shown promising results in boosting GAP43 expression in the diabetic retina." (PMID 39845838, 2024). "In conclusion, the present study shows that diabetes decreases GAP-43 and KIF5B protein levels in gastrocnemius muscle of STZ-induced diabetic rats and as a non-pharmacologic therapeutic intervention, ET can modify it." (PMID 33953268, 2021). "The results of present study point to the fact that diabetes decreases GAP-43 protein levels in gastrocnemius muscle." (PMID 33953268, 2021). "In diabetes, GAP43 axons were dramatically reduced in numbers both around the wound sites and into new tissue as new nerve sprouts." (PMID 24098736, 2013). "While lifestyle factors (e.g., smoking and alcohol consumption) and comorbidities (e.g., diabetes) were associated with higher GAP-43 protein levels, these factors were not independently significant when adjusted in the multivariate analyses." (PMID 40004753, 2025). "In this regard, GAP-43 and KIF5B protein levels in the DC group were significantly lower than those in the C group, indicating that diabetes caused a decreased expression of these proteins in the gastrocnemius skeletal muscle fibers (p ≤ 0.001 and p ≤ 0.001, respectively)." (PMID 33953268, 2021). "BMI, diabetes, smoking, and alcohol consumption were identified as significant predictors of GAP-43 levels, particularly in the study group, suggesting that these factors may contribute to the molecular changes observed in degenerative yellow ligamentum flavum." (PMID 40004753, 2025). "In conclusion, this study highlighted the potential of GAP-43 as a biomarker for pain severity and disease progression in degenerative spinal stenosis, while also emphasizing the influence of lifestyle factors such as smoking and alcohol consumption, as well as comorbid conditions such as diabetes." (PMID 40004753, 2025). "Therefore, we propose that the beneficial effects of ET on diabetes might be related to GAP-43 and KIF5B expression and their co-localization in skeletal muscle." (PMID 33953268, 2021). "However, the exact mechanism of muscle hypertrophy through exercise training and the role of GAP-43 in diabetes remains unclear." (PMID 33953268, 2021). "Another research suggested that luteolin could ameliorate the cognitive dysfunctions in STZ-induced diabetic rat model by downexpression of glycation end products (AGEs), inhibition of IL-1 and TNF- and upregulating the expressions of GAP-43 and SYN." (PMID 33292335, 2020).
diabetes (continued). "Although GAP-43 evaluation has not been studied in skeletal muscle fibers of diabetic rats, several studies have indicated that this protein undergoes major changes in diabetes state." (PMID 33953268, 2021). "However, there is no finding related to GAP-43 changes in skeletal muscles in diabetes." (PMID 33953268, 2021).
depression (12 papers, 2018 to 2025). "Previous studies have identified ELAVL4 as an RBP targeting several neuroplasticity-related mRNAs, including Bdnf, Ngf, Gap-43, and Nrn1, all of which are closely associated with neuroplasticity and have well-established links to depression." (PMID 39940881, 2025). "Several studies have suggested that depression is associated with alterations in GAP-43 expression in the brain, indicating abnormalities in neuronal plasticity, but these studies have been inconsistent in their findings." (PMID 29707580, 2018). "MARCKS and GAP-43 have been shown to play a role in depression and have been studied in postmortem brains of depressed and suicidal patients." (PMID 33515455, 2021). "HG increased NCAM and GAP-43 protein expression in the hippocampus in the animal model of depression." (PMID 32308703, 2020). "Previous studies have demonstrated that GAP-43, a neuromodulin, is involved in the pathophysiology of depression and the mechanisms of antidepressants." (PMID 32123521, 2020). "Another study investigated the effect of chronic treatment with fluoxetine on neurogenesis and the expression of growth-associated protein 43 (GAP43), a synaptic protein, in the hippocampus of rats exposed to chronic unpredictable mild stress (CUMS), a behavioral model of depression." (PMID 39767650, 2024). "Moreover, depression-like and anxiety-like behaviors were related to the abnormal expressions of synapse-associated proteins, including PSD-95, GAP-43, and SYN." (PMID 33746787, 2021). "The evidence that PKC may also be involved in depression is based on the observation that treatment with antidepressants increased phosphorylation of PKC substrates such as GAP-43 and MARCKS." (PMID 33515455, 2021). "PSD-95, SYN, and GAP-43 proteins are markers of synaptic plasticity in depressive disorder." (PMID 32174832, 2020). "In addition, we studied the impact of CMS on 5-HT and GAP-43 expression in order to gain insight into the possible mechanisms by which chronic stress-induced depression might lead to the occurrence of cardiovascular disease." (PMID 29707580, 2018). "Hence, it can be hypothesized that changes in GAP-43 expression and neuronal plasticity are another potential mechanism linking depression and cardiovascular disease." (PMID 29707580, 2018). "Immunofluorescence also verified the elevated expression of GAP43 and TH in CUS, suggesting autonomic dysfunction in the CUS-induced rat model of depression." (PMID 38261756, 2024). "The same results showed that learned helplessness paradigm, as an accepted experimental model of depression, decreased the immunostaining of SYN, PSD-95, and GAP-43 in the CA3 region of the hippocampus of model animals." (PMID 32174832, 2020). "In addition, SNS reversed the reduced expression of PSD95, SYN, neuroligin-1 and GAP43 proteins in the DRN brain region MS co-CUMS model, in line with previous depression models and some antidepressant research." (PMID 40469980, 2025). "Overall, exercise can promote the expression of BDNF and CREB by increasing SIRT1 expression in the hippocampus, and moreover, it can activate the SIRT1/IGF-1/GAP-43 and SYN signaling pathways to increase the volume of SVZ and SGZ, improving neurogenesis, and eventually relieving depression." (PMID 37239191, 2023). "Similarly, reduced HRV and increased expression of GAP43 and TH were also found in CUS-induced mice, whereas P2X7R-KO significantly mitigated these indicators, validating the dysfunction of ANS in depression and the protective effects of P2X7R in regulating ANS." (PMID 38261756, 2024).
epilepsy (12 papers, 2017 to 2025). A brain disorder characterized by episodes of abnormally increased neuronal discharge resulting in transient episodes of sensory or motor neurological dysfunction, or psychic dysfunction. "We aimed to investigate the serum levels of growth-associated protein-43 (GAP-43) and neurotrophin-3 (NT-3) among cohort of Egyptian children with epilepsy and correlate these biomarkers with their zinc levels." (PMID 35349008, 2023). "We previously showed increased growth associated protein 43 (GAP-43) expression in brain samples resected from patients with cortical dysplasia (CD), which was correlated with duration of epilepsy." (PMID 29255203, 2017). "We have recently shown that the duration of epilepsy in patients with CD is correlated with increased expression of growth-associated protein 43 (GAP-43), a marker of axonal and synaptic growth." (PMID 29255203, 2017). "In addition, Gap43 seems to be linked with mossy fiber sprouting in experimental models of epilepsy." (PMID 28758946, 2017). "As regards the performance characteristics of GAP-43 in diagnosing epilepsy at cut-off point ≤ 0.6 ng/mL showed 78% sensitivity, 62% specificity, positive predictive value (PPV) = 50.6%, negative predictive value (NPP) = 84.9% with AUC = 0.574." (PMID 35349008, 2023). "The findings presented in this study provide valuable insight into some possible molecular mechanisms of epileptogenesis and identify GAP-43 as a potential new target protein for the treatment and prevention of epilepsy in cortical dysplasia." (PMID 29255203, 2017). "Together, these results suggest GAP-43 as a key factor promoting epileptogenesis, a possible therapeutic target for treatment of progressive epilepsy and a potential biomarker for epilepsy progression in CD." (PMID 29255203, 2017). "Growth associated protein ‐43 (GAP‐43 is a calmodulin (CaM)‐binding protein exclusively present in the excitatory neurons in the nervous system, found upregulated in conditions like epilepsy." (PMID 40709526, 2025). "A study of lithium–pilocarpine-induced epilepsy in rats found that treatment with LEV reduced the GAP43 levels in a dose-related fashion, theorizing that reduction in axonal sprouting may be a mechanism for LEV's antiepileptogenic functions." (PMID 33584493, 2020). "Changes of GAP-43 expression levels in experimental models of epilepsy and traumatic brain injury urges for additional investigations of CSF GAP-43 change in epilepsy and traumatic brain injury patients to find out the potential use of GAP-43 concentration as a neuronal injury biomarker." (PMID 30526557, 2018). "GAP-43 in serum is also increased in CD rats that developed spontaneous epilepsy." (PMID 29255203, 2017). "With an increase in excitatory neurotransmission through glutamate receptors, GAP-43 may be further upregulated, creating more excitatory synapses and a potential positive feedback loop in epilepsy-prone brains." (PMID 29255203, 2017). "This rather specific expression of GAP-43 may point to a fundamental pathophysiological mechanism for expression of epileptogenicity and disease progression in epilepsy due to CD." (PMID 29255203, 2017). "GAP-43 can be considered a sensitive good negative biomarker in childhood epilepsy which correlated positively with the zinc status." (PMID 35349008, 2023). "While EEG seizure activity (epilepsy-like spikes) was induced in all animals, THC injection increased the latency to tonic-seizure onset and decreased interictal-spike frequency selectively in Glu-Gap43−/− mice compared to vehicle-treated littermates." (PMID 37085487, 2023). "GAP-43 may have a key part in the pathogenesis of epilepsy in children, and it can be utilized to rule out epilepsy in children who experience seizures." (PMID 35349008, 2023).
ischemic stroke (11 papers, 2015 to 2025). A stroke disorder caused by obstruction of blood flow to the brain, due to thrombotic (local blood clot formation) or embolic (due to a blood clot or other material traveling from another site) event. "A monoclonal antibody that targets the growth-associated protein-43 (GAP43) has been employed to direct extracellular vesicles towards the extracellular environment of damaged neurons in an ischemic stroke model." (PMID 41190075, 2025). "The incidence of ischemic stroke in the context of vascular disease is high, and the expression of growth-associated protein-43 (GAP43) increases when neurons are damaged or stimulated, especially in a rat model of middle cerebral artery occlusion/reperfusion (MCAO/R)." (PMID 34001136, 2021). "Our study showed that the upregulation of Gap43 after the CIR-induced ischemic stroke may be caused by a self-repairing mechanism in the brain." (PMID 26492191, 2015). "Subsequent immunohistochemical staining in tissues from 1-week post-ischemic stroke and control marmosets, revealed an increased number of astrocytes colocalizing NogoA and either GAP43, KLF6, or CD44, consistent with the transcriptomic results." (PMID 34824275, 2021). "The axonal sprouting process is accompanied by high expression of GAP-43 after ischemic stroke." (PMID 36741282, 2023). "As the survival of neurons in the penumbra is neuroprotective in ischemic stroke, we first determined whether Que/mAb GAP43-Exo exerted neuroprotective effects against OGD-induced cell injury by performing LDH assay and TUNEL assay." (PMID 34001136, 2021). "Growth-associated protein 43 (GAP-43) and neurofilament 200 (NF-200) promote axonal regeneration and synaptic plasticity, while paired immunoglobulin-like receptor B (PirB) inhibits neuronal burst growth by activating RhoA, thereby suppressing motor function recovery after ischemic stroke." (PMID 40881626, 2025). "It was found that GAP-43 and CASP3 are involved in the neurogenesis of lesions after ischemic stroke." (PMID 36741282, 2023).
brain injury (10 papers, 2011 to 2024). Acute and chronic (see also brain INJURIES, CHRONIC) injuries to the brain, including the cerebral hemispheres, CEREBELLUM, and brain STEM. "The ability to regenerate after ischemic brain injury is closely related to the enhancement of mTOR/p-S6 activity, which increases the expression of growth associated protein-43 (GAP-43)." (PMID 37426810, 2023). "GAP43 expression was shown to be inversely associated with the intensity of neuronal injuries in mice (i.e., increased and decreased expression following moderate and severe brain injury, respectively)." (PMID 23874584, 2013). "Traumatic brain injury in rats results in increased expression of Gap-43 that correlates with behavioral recovery." (PMID 34223546, 2021). "Level of proteases such as thrombin, trypsin, tryptase, and specific neuronal proteases, including P22 and B-50/GAP-43 (SFRB60) within the CNS are increased following brain injuries and because of blood-brain barrier dysfunction." (PMID 24250922, 2013). "Several studies have shown, using transgenic mice, that overexpression of GAP-43 induces axonal sprouting, suggesting that it represents an appealing target to promote central nervous system repair following brain injuries." (PMID 21695168, 2011). "Increased GAP-43 expression may be correlated with Nogo-A inhibition after traumatic brain injury in rats." (PMID 24265694, 2013).